TMEM216 (transmembrane protein 216)
Description:
Essential for primary ciliogenesis and embryonic development, facilitating the activation of Hedgehog (Hh) signaling pathway. Disrupts the interaction of GLI2 and GLI3 with the negative regulator SUFU. Inhibiting SUFU's interaction with GLI2 promotes the entry of GLI2 into the nucleus, allowing it to activate Hh target gene expression. Disrupting SUFU's interaction with GLI3 prevents its conversion into the repressor form, leading to increased nuclear GLI3 and enhanced Hh signaling. Required for the proper development and structural integrity of photoreceptor outer segment disks, ensuring normal outer segment morphogenesis and survival of photoreceptors.
Synonyms: HSPC244; MGC13379; JBTS2; RP98; formerly CORS2; MKS2
Tractability: Antibody: UniProt predicts a signal peptide or a membrane-spanning region.
Gene: Protein-coding gene on chromosome 11 (61,392,393 to 61,398,866, forward strand). Ensembl gene ENSG00000187049.
Subcellular location: Membrane; Cytoplasm, cytoskeleton, cilium basal body
Pathways (Reactome):
Organelle biogenesis and maintenance: Anchoring of the basal body to the plasma membrane
Gene Ontology:
Molecular function: protein binding
Biological process: cilium assembly; non-motile cilium assembly; photoreceptor cell maintenance; photoreceptor cell morphogenesis; positive regulation of cilium assembly; positive regulation of smoothened signaling pathway; protein localization to ciliary transition zone
Cellular component: cilium; ciliary transition zone; cytosol; MKS complex; membrane
Genetic constraint (gnomAD): Loss-of-function variants: 12 observed, 13.35 expected, observed/expected ratio (o/e) 0.9, 90% interval 0.57 to 1.45. The upper end of that interval is the gene's LOEUF score, 1.45, which puts it in group 6 of 6, group 1 being the genes least tolerant of losing a copy. Missense variants: 144 observed, 162.48 expected, observed/expected ratio (o/e) 0.89, 90% interval 0.77 to 1.02. Synonymous variants: 53 observed, 71.47 expected, observed/expected ratio (o/e) 0.74, 90% interval 0.59 to 0.93.
Gene-disease validity (ClinGen):
ClinGen rates the evidence that TMEM216 causes each of these diseases.
ciliopathy (autosomal recessive): Definitive. A genetic disorder of the cellular cilia or the cilia anchoring structures, the basal bodies, or of ciliary function.
Homologues: Orthologues: chimpanzee TMEM216 (99% identical), macaque TMEM216 (97% identical), dog TMEM216 (90% identical), pig TMEM216 (89% identical), mouse Tmem216 (88% identical), guinea pig TMEM216 (87% identical), rat Tmem216 (86% identical), zebrafish tmem216 (56% identical), Caenorhabditis elegans mks-2 (29% identical), Drosophila melanogaster CG11760 (29% identical), Drosophila melanogaster TMEM216 (28% identical). Paralogues in human: TMEM80 (39% identical), TMEM17 (23% identical).
Diseases named in the same sentence as TMEM216 in open-access papers:
TMEM216 is named in the same sentence as 35 diseases in open-access papers, as found by Europe PMC text mining. Sharing a sentence is not in itself a finding about the gene and the disease. The quoted sentences say what the papers report.
ciliopathy (16 papers, 2012 to 2026). "Mutations in TMEM216 and other genes encoding ciliary components cause ciliopathies, indicating that dysfunction in the transition zone is a common pathogenic mechanism underlying these disorders." (PMID 40365501, 2025). "Mutations in the TMEM216 gene, a pathogenic variant associated with ciliopathy, have been implicated in severe renal impairment." (PMID 40365501, 2025). "RhoA has been shown to contribute to the molecular pathology of ciliopathies: increased RhoA levels were observed in dermal fibroblasts from ciliopathy patients with TMEM216 mutations." (PMID 33392209, 2020). "For example, several small tetraspanin-like transmembrane proteins (TMEMs) that are mutated as a cause of MKS and other ciliopathies (TMEM216, TMEM231, and TMEM107) appear to localize to the specialized ciliary membrane at the TZ." (PMID 29209597, 2017). "TCTN1 is also a known protein component of a ciliopathy-associated protein complex and could interact with Mks1, Tmem216, Tmem217, and several other proteins that are associated with ciliopathies to modulate ciliary assembly and trafficking." (PMID 31297133, 2019). "In all, the six ciliopathy‐associated residues in TMEM17 and TMEM216 are among the most conserved, and in TMEM17 cluster within the second helix of the four‐transmembrane‐domain structure." (PMID 40841990, 2026). "Studies in Caenorhabditis elegans revealed that TMEM216 functions as part of the transition zone (TZ) module, contributing to the spectrum of ciliopathy phenotypes." (PMID 40365501, 2025). "The TMEM216-SUFU-GLI2/GLI3 axis plays an essential role in ciliopathies and aberrant Hedgehog (Hh) signaling induced by TMEM216 deficiency." (PMID 40365501, 2025). "Meanwhile, further investigations into the role of TMEM216 in kidney diseases, particularly in tubular injury, interstitial fibrosis, and other ciliopathies—may provide critical insights into the molecular mechanisms underlying renal pathophysiology and reveal novel therapeutic targets." (PMID 40365501, 2025). "TCTN1, for example, forms a biochemical complex at the TZ with CC2D2A, other ciliary transmembrane proteins (TCTN2, TMEM216, and TMEM67), and other known ciliopathy proteins (MKS1, CEP290, and B9D1)." (PMID 29209597, 2017). "Of the 30 ciliopathy genes tested, knockdown of four genes (BBS1, BBS7, BBS10 and TMEM216) resulted in disruption of the apical–basal polarity of RG cells." (PMID 26206566, 2015). "The four ciliopathy genes (BUBR1 [BUB1B], IFT80, KIF7 and TMEM216) we identified as modifiers of progenitor proliferation encode proteins localized to distinct ciliary compartments." (PMID 26206566, 2015). "We also observed that knockdown of ciliopathy genes ALMS1, BUBR1 [BUB1B], IFT80, NPHP1, NPHP8 [RPGRIP1L], TCTN2, TMEM216 and TUB retarded neuronal migration." (PMID 26206566, 2015). "Taken together, these results indicate that different ciliopathy-specific genes (BBS1, BBS7, BBS10 and TMEM216) modulate distinct aspects of apical–basal polarity of the RG scaffold and the integrity of the proliferative niche organization." (PMID 26206566, 2015). "The regulation of TMEM216 expression by F11R and PGRMC2 may partially explain the ciliopathy phenotypes seen in zebrafish model." (PMID 32832346, 2020).
Joubert syndrome (8 papers, 2011 to 2025). Joubert syndrome (JS) is characterized by congenital malformation of the brainstem and agenesis or hypoplasia of the cerebellar vermis leading to an abnormal respiratory pattern, nystagmus, hypotonia, ataxia, and delay in achieving motor milestones. "Mutations in TMEM216 are closely associated with disorders such as Joubert syndrome and Meckel syndrome, which are characterized by multisystem abnormalities including neurodevelopmental defects, renal anomalies, and retinal degeneration." (PMID 40365501, 2025). "Mutations in TMEM216, a ciliary transition zone tetraspan transmembrane protein, are linked to Joubert syndrome and Meckel syndrome." (PMID 32687549, 2020). "TMEM216 is required for cilia assembly and TMEM216 mutations also cause Joubert syndrome in humans." (PMID 33435268, 2021). "Very recently, it has been found that Joubert syndrome and related disorders, whose clinical picture includes liver fibrosis, is due to a defect in the TMEM216 gene (a protein involved in ciliogenesis and centrosomal docking)." (PMID 22022514, 2011).
Meckel-Gruber syndrome (8 papers, 2013 to 2025). "Knockdown or mutation of Tmem216 (transmembrane protein 216), a gene mutated in Joubert and Meckel syndromes, resulted in ciliogenesis defects, and impaired centrosome docking to cilia due to the mislocalization of hyperactivated RhoA." (PMID 24027500, 2013). "TMEM216 is one of the disease-causing genes for Meckel-Gruber syndrome (MKS)." (PMID 40365501, 2025). "Clinically, patients with Joubert or Meckel syndrome may present with progressive decline in renal function, suggesting that TMEM216 mutations may contribute to renal pathologies in these syndromes by impairing ciliogenesis." (PMID 40365501, 2025). "Interestingly, two OFDVI patients were reported to have a homozygous mutation in TMEM216, a gene implicated in JSRD and Meckel-Gruber syndrome (MKS), and a mutation in the OFD1 transcript has been reported in an OFDVI case." (PMID 24884629, 2014).
melanoma (2 papers, 2015 to 2023). A malignant, usually aggressive tumor composed of atypical, neoplastic melanocytes. "TMEM216 is the melanoma gene with the most significant synonymous somatic mutations of the TCGA SKCM dataset." (PMID 25600636, 2015). "In the context of this study aimed at characterizing the genomic landscape of melanoma, there is space to discuss somatic mutations of two new, highly significant genes, TMEM216 and LUZP2." (PMID 25600636, 2015). "In addition, recurrent somatic mutations driving alternative splicing of TMEM216 are significantly associated with melanoma in The Cancer Genome Atlas (TCGA), suggesting possible tumor suppressor function for this gene." (PMID 36829244, 2023). "TMEM216 stands out among the newly discovered genes in melanoma as a low-frequency, highly statistically significant, recurrent splice site mutation." (PMID 25600636, 2015). "In the context of melanoma, somatic splice-site mutation of TMEM216 suggests potential tumor suppressor function and sets the RHOA/GNA12 pathway apart from the Gs-protein/MAPK pathway by mutual exclusivity of TMEM216 towards known oncogenes NRAS and RAC1." (PMID 25600636, 2015).
cyst (1 paper, 2025). A sac-like closed membranous structure that may be empty or contain fluid or amorphous material. "In addition, gene therapy approaches such as antisense oligonucleotide (ASO) technology have shown promising results in reducing cyst formation in CEP290-related renal disease models and may represent a potential precision treatment strategy for TMEM216-related kidney disorders in the future." (PMID 40365501, 2025).
microcephaly (1 paper, 2015). A congenital or acquired developmental disorder in which the circumference of the head is smaller than normal for the person's age and sex. "Our observation of disrupted neural progenitor proliferation in BUBR1 [BUB1B]- and TMEM216-deficient brains is consistent with the clinical symptoms, such as microcephaly, found in human patients." (PMID 26206566, 2015).
Nephropathy (1 paper, 2025). A nonspecific term referring to disease or damage of the kidneys. "Future research on TMEM216-related nephropathy should aim to further elucidate its pathogenic mechanisms and explore potential therapeutic targets to enhance patient outcomes and advance precision medicine." (PMID 40365501, 2025).
Renal cyst (1 paper, 2025). A fluid filled sac in the kidney. "In our reported case, the patient exhibited primarily renal phenotypes—renal cysts and renal failure—alongside intellectual developmental difficulties, highlighting the possibility that TMEM216 mutations can manifest predominantly as renal disease." (PMID 40365501, 2025).
Renal insufficiency (1 paper, 2025). A reduction in the level of performance of the kidneys in areas of function comprising the concentration of urine, removal of wastes, the maintenance of electrolyte balance, homeostasis of blood pressure, and calcium metabolism. "The current therapeutic principles for TMEM216 mutation–associated renal insufficiency primarily include delaying disease progression, renal replacement therapy (RRT), and reducing the risk of complications." (PMID 40365501, 2025). "The combination of clinical and genetic findings suggests that the patient’s renal insufficiency may be attributed to TMEM216 mutations, highlighting their potential role in the progression of CKD." (PMID 40365501, 2025).
scoliosis (1 paper, 2024). A congenital or acquired spinal deformity characterized by lateral curvature of the spine. "Indeed, Cep290 is markedly decreased in mak mutants, so it is possible that scoliosis and smaller body size in mak mutants are caused by reduced activity of Cep290 and Tmem216, respectively." (PMID 38813692, 2024).
renal disease (3 papers, 2022 to 2025). "Through genetic testing and an analysis of family history, a diagnosis of hereditary kidney disease due to a mutation in the TMEM216 gene was established." (PMID 40365501, 2025). "Similarly, the same founder variant p.R73C in the TMEM216 gene causes a JS phenotype that can be entirely neurological or variably associated to polydactyly, renal disease, oral‐facial‐digital features, and retinopathy." (PMID 35238134, 2022).
TMEM216 also shares sentences with these, for which no sentence is quoted: tumor (2 papers); aortic stenosis (1); Bardet-Biedl syndrome (1); breast carcinoma (1); developmental delay (1); frontometaphyseal dysplasia (1); holoprosencephaly (1); Joubert syndrome and related disorders (1); Leber congenital amaurosis (1); left ventricular hypertrophy (1); Leukoencephalopathy (1); liver fibrosis (1); Meckel syndrome type 13 (1); Meckel syndrome, type 2 (1); nephronophthisis (1); osteofibrous dysplasia (1); polydactyly (1); primary ciliary dyskinesia (1); renal failure (1); retinal degeneration (1); retinopathy (1); spondylometaphyseal dysplasia (1); Walker Warburg syndrome (1); Zellweger syndrome (1).